CCL3 (C-C motif chemokine ligand 3)
Diseases named in the same sentence as CCL3 in open-access papers (continued):
Sharing a sentence is not in itself a finding about the gene and the disease.
COVID-19 (continued). "The analysis of cord blood samples at Early and Intermediate convalescent COVID-19 showed increased levels of CCL11, CCL3, CCL4, CCL2, IL-1β, IFN-γ, IL1-Ra, G-CSF, and IL-7 and a decrease of IL-10 and IL-2 as compared with HC." (PMID 40821818, 2025). "Our data reveal a shift towards a pro-inflammatory M1 phenotype in severe COVID-19 cases, with elevated expression of TNFα, IL1β, CCL2, and CCL3, which are markers of classical activation and inflammation." (PMID 39928675, 2025). "We note the differential expression of many inflammatory CC chemokines (CCLs) in severe COVID-19, including CCL2, CCL3, CCL8, CCL3L1 and CCL7, and CXC chemokines such as CXCL2 and CXCL8." (PMID 39187683, 2024). "Cytokine profiling of the sera of patients with COVID-19 and the transcriptional analysis of their BAL fluid revealed increased IL-6, G-CSF, CXCL10, CCL2, CCL3, and TNF-α levels, correlating with disease severity and progression." (PMID 39417078, 2024). "CCL3, CCL5, CXCL2, and CXCL10 have been reported to be increased in patients with severe COVID-19-related acute respiratory distress syndrome (ARDS)." (PMID 38584257, 2024). "Transcriptomic studies of COVID-19 patients revealed upregulated cytokine (TNF, CXCL8, IL1B, IL6, IL10, IL12) and chemokine (CCL2, CCL3, CCL4, CCL20, CXCL2, CXCL9, CXCL10) expression in monocytes as one major dysregulation in these patients." (PMID 38391913, 2024). "Leukocytes from cultures of patients with severe COVID-19 at endpoint A showed hypomethylation of the chr17: 36,090,102 locus, in the 5’ UTR region of CCL3, when compared to the CTRL group." (PMID 36993968, 2023). "We also examined the expression of previously reported inflammatory cytokines (TNF, IL6, IL1B, CCL3, CCL4 or CXCL2) produced by circulating monocytes in patients with COVID-19." (PMID 37363730, 2023). "For instance, analysis of transcriptomic data in bronchoalveolar lavage of a patient with COVID-19 found high expression of CCL2, CCL3, CCL4, and CXCL10 when compared to healthy donors." (PMID 37632046, 2023). "Monocytes from HD + COVID-19 patients showed an enhanced capacity for pro-inflammatory cytokine production, with GM-CSF, IL-1β, IL-8, IL-10, CCL2 and CCL3 as the most increased cytokines compared with uninfected HD patients." (PMID 36675231, 2023). "Among the genes most refractory to glucocorticoid treatment, CCL3 and IL1B stand out, both with a central role in the pathophysiology of COVID-19 and highly expressed in peripheral blood mononuclear cells during the disease." (PMID 36993968, 2023). "In severe cases of COVID-19, multiple studies have indicated higher levels of IL-2, IL-6, IL-7, IL-10, CXCL10(IP-10), CCL2 (MCP-1), TNF-α, CCL3(MIP-1α), and G-CSF when compared to patients with mild and moderate infections." (PMID 37834246, 2023). "Remarkably, severe influenza and COVID-19 also converge in elevated levels of chemotactic (CXCL8, CCL2, CCL3, and CXCL10) and activating molecules (G-CSF) acting on monocytes and neutrophils." (PMID 35674675, 2022). "Further studies are warranted to determine surface IDE levels in different subsets of disease-related classical monocytes and its relevance in regulating CCL3 and CCL4 levels in COVID-19 patients." (PMID 36232381, 2022). "In another clinical investigation, COVID-19 patients requiring ICU admission exhibited higher levels of CXCL10, CCL2, CCL3, and CCL7 compared to mildly infected patients." (PMID 36016187, 2022). "The findings showed that compared to healthy controls, patients with COVID-19 had significantly higher levels of interleukins 1α, 2, 6, 7, 8, 10 and 15, CRP, SAA, ICAM-1, VCAM-1, CXCL10, CCL3, CCL26, IFN-γ, TNF-α, bFGF, PlGF, and Flt-1." (PMID 35958594, 2022). "In order to improve and simplify the efficacy of prediction and diagnosis of CU, especially COVID-19-related CU, we identified three key genes (FCGR3A, CCL3, and TNF) from hub genes by the machine learning LASSO regression analysis." (PMID 36531995, 2022).
COVID-19 (continued). "In post-COVID-19 patients, some plasma cytokines (i.e. TNF-α, IL-18, CXCL8, CXCL10, CCL2, CCL3, and CCL4) remained higher than in HCs, but levels were much lower as compared to hospitalised patients." (PMID 36275702, 2022). "MMP-7, TGF-β, CCL2, CCL-3, CXCL-10, G-CSF, IFN gamma, IL-10, IL-2, IL-4, IL-6, IL-7, TNF-α, IL-6, and IGF-1 were studied for their correlation to lung involvement in COVID-19 patients." (PMID 36286038, 2022). "COVID-19 patients show higher concentrations of IL-2, IL-7, IL-10, G-CSF, IP10 (CXCL10), MCP-1 (CCL2), MIP1a (CCL3) and TNF-α than non-COVID-19 patients." (PMID 35901034, 2022). "Our research further displayed that all the key genes (CCL3, TNF, and FCGR3A) were statistically related to central infiltration cells (e.g. mast cells and macrophages M0) in CU and COVID-19." (PMID 36531995, 2022). "Recently, it has been reported that CCL3 and CCL4 are significantly upregulated at later stages of the disease in patients with severe COVID-19." (PMID 36232381, 2022). "Monocytes and macrophages accumulate in lung of severe COVID-19 patients, exhibit hyperinflammatory signatures, produce chemokines, such as CCL2 and CCL3; their frequency is correlated with older age and mortality." (PMID 35710943, 2022). "Data analysis demonstrated an increased order of magnitude (≥3x) for CXCL8, CCL3, IL-6, IFN-γ, G-CSF and decreased order of magnitude (≤0.3x) for CCL11, IL-4, IL-5, IL-10, PDGF and IL-7 in COVID-19 patients throughout the kinetic follow-up." (PMID 36451835, 2022). "MMP-7, TGF-β, CCL2, CCL-3, CXCL-10, G-CSF, IFN gamma, IL-10, IL-2, IL-4, IL-6, IL-7, TNF-α, IL-6, and IGF-1 were studied for their correlation with mortality in all 40 COVID-19 patients." (PMID 36286038, 2022). "The disease is also associated with the elevated blood levels of other chemokines such as CCL2/MCP-1, CCL3/MIP-1α, CCL4/MIP-1β, CXCL9/MIG, CXCL10/IP-10 and CX3CL1/Fractalkine, which shows that CXCL1 is only one of many COVID-19 factors." (PMID 36613652, 2022). "An increased expression of CCL3, CCL4, CSF2, IL1B, and LTA was found in the revaccinated groups (groups 5 and 6), which in fact experienced decreased expression in severe COVID-19 patients." (PMID 36225326, 2022). "Plasma levels of IL-1RA, IL-10, IL-15, and G-CSF and of the chemokines CCL3, CCL4, CXCL8, and CXCL10 were significantly increased in patients with COVID-19 compared with those of healthy controls." (PMID 34793331, 2022). "Lower expression of chemokine CCL3 and cytokine IL1B12, and higher expression of the myeloid cell plasticity regulator KLF613 were observed in both IgG− and IgG+ COVID-19 subjects." (PMID 35810186, 2022). "We also observed increased levels of CCL5 and CCL3, expressed in NK cells, that interact with the CD191 receptor (CCR1), and whose inhibition potentially suppresses immune hyperactivation in critical COVID-19 patients." (PMID 36443794, 2022). "With regards to circulating chemokine levels, CCL3, CXCL9, CCL20, and CXCL1 were significantly upregulated in samples from individuals with severe COVID-19 when compared against mild and moderate cases." (PMID 34957382, 2022). "Alongside, we observed a high expression of cytokines (CCL3, CCL4, CCL5, CCL7, CCL18 and CCL20) in the CD4+ TCM, Classical monocytes and NK cells in the COVID-19 patients." (PMID 36532041, 2022). "(2020) have observed that patients hospitalized due to their severe COVID-19 have high levels of CCL2/MCP-1 and CCL3 serum." (PMID 36685603, 2022). "Analysis of cytokine and chemokine expression levels revealed higher IL-1β, IL-6, TNF, and CCL2, CCL3, CCL4, and CCL7 in severe COVID-19 BALF compared to moderate disease." (PMID 35401519, 2022). "After stimulating myeloid blood cells with R848, we observed that multiple myeloid subsets from COVID-19 patients had lower levels of IFNβ and higher levels of TNF, IL-6, IL-12, CCL3, and CCL4 than cells from healthy controls." (PMID 36085197, 2022).
COVID-19 (continued). "This also showed that stimulation post-BCG vaccination increased expressions of BIRC3, CCL3, CCL3L1, CCL4, CSF2, IL1B, and LTA, which in contrast, decreased in severe COVID-19." (PMID 36225326, 2022). "Significantly, the hyperinflammatory subtype of monocytes express CD14 and CCL3, which broadly express more cell-type-specific cytokines, and this might be one of the major sources in PBMCs triggering the inflammatory cytokine storm in severe COVID-19 patients." (PMID 34975921, 2021). "The latest laboratory findings from Wuhan patients also showed that mild COVID-19 patients had elevated levels of IL-1B, IFNγ, CXCL10, and CCL2, whereas in severe cases, G-CSF, CXCL10, CCL2, and CCL3 were elevated." (PMID 34441862, 2021). "Analyses performed in the BAL fluids showed that the chemokines CCL3 and CCL5 and the proinflammatory molecules IL-1β and IL-6 were significantly higher in patient 1 compared to the non-COVID-19 bLTx patient." (PMID 33801959, 2021). "When COVID-19 progresses to severe illness, an immune system overreaction that culminates in abnormally increased serum levels of CCL2, CCL3, and CXCL10, has been reported." (PMID 33669011, 2021). "The increase in blood concentrations of different cytokines such as interleukins and chemokines such as IL-6, IL-8, IL-10, TNF-α, IL-1β, IL-2, IP-10, MCP-1, CCL3, CCL4, and CCL5 has been described for COVID-19 patients." (PMID 34262570, 2021). "Although the profile of inflammatory markers is highly variable between patients, a general phenotype of severe COVID-19 is characterized by elevated IL-6, IL-8, IL-10, TNF-alpha, CCL2, CCL3, and CXCL8." (PMID 34830356, 2021). "In severe COVID-19 lung macrophages displayed high expression of IL-1β, IL-6, TNF-α and various chemokines (CCL2, CCL3, CCL4, CCL7, CXCL9, CXCL10 and CXCL11)." (PMID 34054832, 2021). "The CXCL10+ CCL2+ inflammatory macrophages displayed significantly higher expression of CXCL10, CXCL11, CCL2, CCL3, GBP1, and IDO1 in severe COVID-19, inflamed RA, and CD compared to the FCN1+ macrophages." (PMID 33879239, 2021). "Compared to healthy controls, CD16+ monocytes from people with COVID-19 had significantly upregulated expression of genes involved in inflammation including cytokines and chemokines, such as IL-1β, CXCL8, CCL3 (MIP-1α), and CCL4 (MIP-1β)." (PMID 34108966, 2021). "This process is modulated by proinflammatory mediators, such as TNFα, CCL3, and CCL2 (MCP-1), leading to hypoxia, ARDS, and possibly death for COVID-19 patients." (PMID 34616396, 2021). "Its chemokine ligands CCL-5 (RANTES), CCL-3, CCL-4 (also known as MIP-1α and 1β, respectively), and CCL-3L1 are upregulated in severe COVID-19 cases." (PMID 33445810, 2021). "Levels of IL-6, IL-10, IL-15, IFN-γ, TNF-α, CCL2, CCL3, CCL4, CCL26, CXCL9 and CXCL10 were significantly elevated both in COVID-19 critical clinical condition and in MAS patients as compared to healthy controls." (PMID 34226537, 2021). "Similar to EVALI, patients with COVID-19 showed elevated levels of several cytokines (CCL2/MCP-1, CXCL10/IP-10, CCL3/MIP-1A, and CCL4/MIP1B) in BALF and peripheral blood mononuclear cells." (PMID 32528233, 2020). "Most patients with severe COVID-19 show significantly elevated serum levels of inflammatory cytokines, such as IL-6 and IL-1, as well as IL-2, IL-17, G-GSF, GM-GSF, IP-10, MCP1, MIP-1a (also known as CCL3), and TNF, known as a cytokine storm." (PMID 32983180, 2020). "The current data suggest that chemokines such as CCL2, CCL3, CCL5, and IP10 are the initiators of the deadly COVID-19 immunopathological pathway." (PMID 32766256, 2020). "In COVID-19, men demonstrated lower expression of cytokines with protective effects against viral infection, including CCL2, CCL3, CCL4 and CXCL16, than women." (PMID 32974111, 2020). "The macrophage cluster-1-derived signature (CCL8, CCL3, CCL2, KLF6, and SPP1) was confirmed to be significantly higher in severe cases of COVID-19 compared to control and mild cases." (PMID 33138195, 2020).
COVID-19 (continued). "In another study, plasma CCL3 and CXCL10 levels were higher in COVID-19 patients with pneumonia and hypoxia requiring oxygen supplementation compared to patients without pneumonia and patients with pneumonia but not experiencing hypoxia." (PMID 33613280, 2020). "Severe cases of COVID-19 also display higher levels of CCL7, CCL3 and CXCL9 compared to mild and moderate cases." (PMID 33613280, 2020). "Moreover, increased fold changes of CCL2, CCL3, IL-1Ra, and VEGF were commonly observed only in convalescent COVID-19 (Early, Intermediate, and Late subgroups) (# below bar charts)." (PMID 40821818, 2025). "We conclude that the observed upregulation of IL1B, CXCL8 and CCL3 in week 2 compared to the later time points is attributable to interindividual patient differences rather than a general feature of convalescent COVID-19 patients." (PMID 38391913, 2024). "In HD + COVID-19 patients serum cytokine levels correlated negatively with PSO days, reaching statistical significance in the case of the neutrophil chemotactic factor IL-8 and the macrophage inflammatory protein-1α CCL3." (PMID 36675231, 2023). "Interestingly, IL-10, CXCL9, CCL3, and VEGF levels were significantly higher in the COVID-19 group than those in the HC group." (PMID 37422499, 2023). "Serum CCL2, CCL3, CCL7, CXCL9, CXCL10, IL-1β and IL-1Ra levels increased in critical COVID-19 patients (n = 11) when compared to both severe COVID-19 patients (n = 25) and moderate COVID-19 patients (n = 14)." (PMID 36941580, 2023). "Pyroptosis was found in COVID-19 patients with increases of IL-1β and IL-18, which further promoted the secretion of pro-inflammatory cytokines such as IL-6, IFN-γ, MCP-1/CCL2, MIP-1α/CCL3, MIP-1β/CCL4." (PMID 37631016, 2023). "For instance, IL1B, NFKB1, NLRP3, PYCARD, and CASP1 are listed in the COVID-19 Disease Map, while there are molecules absent from it, including CCL3, 3L1, 4L2, CXCL1, 2, 3, 5, 16, TNFAIP6, C15orf48, TMEM176A/B, NFE2, PADI4, RAB20, ETS2, PHLDA2, FOLR3, and HP." (PMID 37719701, 2023). "Controversially, another study indicated that in severe COVID-19 cases, peripheral blood monocytes significantly increased expression of IL-6, TNF, IL-1β, and their receptors, as well as pro-inflammatory chemokines including CCL2, CCL3, and CCL4." (PMID 35632823, 2022). "CCL3 and CXCL10 levels were higher in LTBI/COVID-19 vs. COVID-19." (PMID 36090983, 2022). "Patients with severe COVID-19 typically have increased serum levels of IL-6, IL-8/CXCL8, CXCL9, CXCL10, TNF-α, MCP1/CCL2, RANTES/CCL5, IL-18, and MIP-1α/CCL3, which promote a sustained pro-inflammatory state that may persist for up to 60 days." (PMID 36289507, 2022). "Findings from mouse models, cellular systems, and samples from patients with SARS-CoV-2-induced COVID-19 have shown massive generation of C5a, CCL chemokines (e.g., CCL2, CCL3, and CCL5), CXCL chemokines (e.g., CXCL9 and CXCL10), and growth factors, i.e., TGFβ, GCSF, GMCSF, VEGF, FGF, and PDGF." (PMID 36430817, 2022). "Transcriptome analysis of BALF samples indicated that the levels of pro-inflammatory chemokines such as CXCL1, CXCL2, CXCL6, CXCL8 (IL-8), CXCL10 (IP-10), CCL2 (MCP-1), CCL3 (MIP-1A), and CCL4 (MIP-1B) are elevated in patients with COVID-19, which correlated with disease severity." (PMID 36111104, 2022). "Moreover, the levels of IL-8, CCL2, CCL3, CCL4, CCL7, CCL12, and CX3CL1 were higher in both the serum and CSF samples of COVID-19 cases with neurological syndrome (NS)." (PMID 35464491, 2022). "Additionally, CCL3 and TNF were found to increase in critically ill patients with COVID-19 and related to increased morbidity and mortality." (PMID 36531995, 2022). "Similarly, proinflammatory M1-like macrophages that express high levels of the chemokines CCL2, CCL3 and CXCL10 are abundant in BAL fluid from patients with severe COVID-19, suggesting a pathologic role for inflammatory lung macrophages in COVID-19 as well." (PMID 35271686, 2022).
COVID-19 (continued). "Therefore, more research on the antagonism of CXCL8, CCL2, CCL3, and CXCL10 in influenza and COVID-19 is required." (PMID 35674675, 2022). "A single-cell study of bronchoalveolar lavage fluid (BALF) in intubated COVID-19 patients identified two inflammatory macrophage subsets—one characterized by CCL2, CCL3, and CXCL10 expression and a second by FCN1 and S100A8—as potential mediators of pathology in this late-stage disease." (PMID 33879239, 2021). "Moreover, a significant correlation between COVID-19 severity and the serum concentrations of IL-1, IL-2, IL-6, IL-7, IL-10, TNF-α, G-CSF, CCL2, CCL3, CXCL8, and CXCL10 has been observed." (PMID 34209845, 2021). "In brief, the scRNA-seq followed by the immune transcriptomic analysis indicated an activation state (through CD69 and HLA class II genes), chemotaxis (e.g., CCL3 and CCL4), an inflammatory state (e.g., NFKBIA, PIK3R1, S100A9, etc.)in T cells, especially in CD8+T cells, in COVID-19 cases." (PMID 33717140, 2021). "In addition to the chemokines MCP-1/CCL2 and MIP-1α/CCL3, which were increased in COVID-19 patients, IL-6 and TNF-α production also depends on NF-κB activation." (PMID 33232303, 2021). "Besides the cytokines, several other small chemical molecules or chemokines such as CCL2 (MCP1), CCL3 (MIP1α), CXCL10 (IP-10) have been reported to be higher in the serum of severely ill patients with COVID-19." (PMID 34066983, 2021). "While CXCL9, CXCL10 and CXCL11 expression levels were increased both in moderate and severe disease compared to healthy levels, IL1β, IL6, TNF as well as CCL2, CCL3, CCL4 and CCL7 were expressed at higher levels in lung macrophages from patients with severe COVID-19." (PMID 34367190, 2021). "Indeed inflammatory chemokines CCL2, CCL3 and CCL4 have been found at higher concentrations in the airways compared to the plasma in patients with severe COVID-19." (PMID 34614036, 2021). "Recent clinical investigation reveals that COVID-19 mild patients had high level of IL1B, IFNγ, CXCL10/IP-10 and CCL2/MCP-1, while patients requiring ICU admission had higher level of GCSF, CXCL10/IP-10, CCL2/MCP-1 and CCL3/MIP-1A." (PMID 32228226, 2020). "Regarding the downregulated geneset, MHC II molecules, including HLA-DQA1, HLD-DRA, HLA-DRB1, HLA-DMB, HLA-DMA, etc., and cytokine/chemokine genes, including IL1B, TNF, CCL3, CCL4, and CXCL8 were expressed at lower levels in COVID-19 patients, especially those with severe diseases." (PMID 33101705, 2020). "Consistently, in this study we found the expression of a large number of cytokines are significantly elevated in COVID-19 patients BALF samples compared to control, including pro-inflammatory cytokines CXCL1, CXCL2, CXCL6, CXCL8, CXCL10/IP-10, CCL2/MCP-1, CCL3/MIP-1A and CCL4/MIP1B." (PMID 32228226, 2020). "Patients with severe COVID-19 show higher serum levels of C-reactive protein, D-dimer and proinflammatory cytokines including IL-6, IL-1β, TNF-α, IL-2, IL-8, IL-17, G-CSF, GM-CSF, IP10, MCP1, and MIP1α (or CCL3) named as cytokine storm." (PMID 33202670, 2020). "Most patients with severe COVID-19 exhibited significantly elevated levels of serum proinflammatory cytokines, including IL-6 and IL-1β as well as IL-2, IL-8, IL-17, G-CSF, GM-CSF, IP10, MCP1, MIP1-α (also known as CCL3), and TNF." (PMID 32984768, 2020). "Serum CCL3 and CCL7 levels were higher in male than female COVID-19 patients." (PMID 33613280, 2020). "The mediators CCL3, CCL4, CCL2, CCL5, IL-12, IL-15, IL-1Ra, and PDGF were higher in healthy volunteers, while the mediators CCL11, CXCL10, IL-1b, IL-6, TNF-a, IFN-g, IL-17, IL-9, IL-10, IL-13, FGF-basic, G-CSF, GM-CSF, IL-7, and IL-2 were increased in COVID-19 positive patients." (PMID 37903875, 2023).